WDPCP (WD repeat containing planar cell polarity effector)
Description:
Probable effector of the planar cell polarity signaling pathway which regulates the septin cytoskeleton in both ciliogenesis and collective cell movements. Together with FUZ and WDPCP proposed to function as core component of the CPLANE (ciliogenesis and planar polarity effectors) complex involved in the recruitment of peripheral IFT-A proteins to basal bodies (By similarity). Binds phosphatidylinositol 3-phosphate with highest affinity, followed by phosphatidylinositol 4-phosphate and phosphatidylinositol 5-phosphate.
Synonyms: hFRTZ; BBS15; C2orf86; FRITZ; CPLANE5; CHDTHP; FRTZ
Tractability: Antibody: UniProt places it where antibodies can reach, with medium confidence; its Gene Ontology location is reachable by antibodies, with medium confidence. PROTAC: ubiquitination databases record sites on it.
Gene: Protein-coding gene on chromosome 2 (63,119,559 to 63,827,843, reverse strand). Ensembl gene ENSG00000143951.
Subcellular location: Cell membrane; Cytoplasm, cytoskeleton, cilium axoneme; Cytoplasm, cytoskeleton, cilium basal body
Subcellular location (Human Protein Atlas): Flagellar centriole; Nuclear bodies; Endoplasmic reticulum
Gene Ontology:
Molecular function: phosphatidylinositol binding
Biological process: embryonic digit morphogenesis; roof of mouth development; tongue morphogenesis; cilium assembly; cilium organization; establishment of planar polarity; establishment of protein localization; intraciliary transport; nervous system development; neural tube development; regulation of cilium assembly; regulation of embryonic cell shape; regulation of protein localization; septin cytoskeleton organization
Cellular component: apical plasma membrane; axonemal basal plate; axoneme; cell cortex; cilium; plasma membrane
Genetic constraint (gnomAD): Loss-of-function variants: 62 observed, 81.6 expected, observed/expected ratio (o/e) 0.76, 90% interval 0.62 to 0.94. The upper end of that interval is the gene's LOEUF score, 0.94, which puts it in group 3 of 6, group 1 being the genes least tolerant of losing a copy. Missense variants: 800 observed, 865.79 expected, observed/expected ratio (o/e) 0.92, 90% interval 0.87 to 0.98. Synonymous variants: 306 observed, 311.37 expected, observed/expected ratio (o/e) 0.98, 90% interval 0.89 to 1.08.
Gene-disease validity (ClinGen):
ClinGen rates the evidence that WDPCP causes each of these diseases.
ciliopathy (autosomal recessive): Definitive. A genetic disorder of the cellular cilia or the cilia anchoring structures, the basal bodies, or of ciliary function.
Homologues: Orthologues: chimpanzee WDPCP (99% identical), macaque WDPCP (92% identical), pig WDPCP (81% identical), rat Wdpcp (76% identical), mouse Wdpcp (76% identical), rabbit WDPCP (72% identical), tropical clawed frog wdpcp (58% identical), zebrafish wdpcp (42% identical), Drosophila melanogaster frtz (27% identical).
Diseases named in the same sentence as WDPCP in open-access papers:
WDPCP is named in the same sentence as 38 diseases in open-access papers, as found by Europe PMC text mining. Sharing a sentence is not in itself a finding about the gene and the disease. The quoted sentences say what the papers report.
Bardet-Biedl syndrome (7 papers, 2014 to 2025). A ciliopathy with multisystem involvement. "In humans, several pathogenic sequence variants in WDPCP have been reported in ciliopathy patients, including Meckel-Gruber syndrome, Bardet-Biedl syndrome (BBS) and orofaciodigital syndromes." (PMID 41268724, 2025). "WDPCP (Fritz) is one of 20 known genes that cause Bardet-Biedl syndrome (BBS), all of which are involved in primary cilia function." (PMID 30967415, 2019). "Interestingly, an additional heterozygous mutation in the WDPCP gene, typically associated with Bardet-Biedl syndrome, was also discovered." (PMID 39398711, 2024). "This is particularly true for WDPCP since mutations may be associated with Bardet-Biedl syndrome 15 (BBS15)." (PMID 25203062, 2014). "We also found a significant missense mutation in WDPCP (p = 3.959e−10) in the female cohort, a mutation which has been previously implicated in typical neuronal functioning through axonal migration and structural reinforcement, as well as in Bardet-Biedl syndrome-15, a ciliopathy." (PMID 34518561, 2021). "Patient #43 had two VUSs in WDPCP identified by WES; variants in this gene have been reported in association with Bardet--Biedl syndrome, which can present with cataracts along with retinal issues." (PMID 36980880, 2023). "In Bardet–Biedl syndrome, TTC8, BBS9, WDPCP, and IFT27 were shared by the two pipelines, and BBS4, BBS7, BBS12, and IFT74 suffered significantly different selective pressures between TG and BG birds." (PMID 35456484, 2022).
ciliopathies (7 papers, 2016 to 2025). "Data generated from this study provide new insight into the structure-function relationship of WDPCP, which is likely to be instrumental in understanding the pathogenesis of WDPCP-associated ciliopathies." (PMID 41268724, 2025). "Several other missense mutations in WDPCP are associated with ciliopathies, and several of these missense mutations (D54N, R55K, L205F, E365G, S708F) do not affect the expression or stability of the mutant WDPCP proteins." (PMID 41268724, 2025). "Pathogenic variants in the ciliogenesis and planar cell polarity effectors (CPLANE) genes FUZZY, INTU and WDPCP disturb ciliogenesis, causing severe ciliopathies in humans and mice." (PMID 38546045, 2024). "Because a variant of W513 (p.Trp513Ser) is associated with Bardet-Beidl syndrome, insight gained into the structure-function relationship may be valuable for understanding WDPCP-associated ciliopathy." (PMID 41268724, 2025). "Importantly, mutations in human homologs of the PCP effectors INTURNED, FUZZY and WDPCP have been associated with several human ciliopathies including Orofacial Digital Syndrome, Joubert Syndrome and Short-Rib-Polydactyly syndrome." (PMID 35076510, 2021). "Interestingly, the unclassified OFD case with mutations in WDPCP also carried a deleterious deletion in IQCB1 which is associated to another ciliopathy, Senior–Loken syndrome, type 5 (SLSN5) characterized by early onset retinopathy and renal disease." (PMID 27141300, 2016). "Intriguingly, many ciliopathy mutations were located outside of the WD40 domains, warranting further exploration of the structures of WDPCP." (PMID 41268724, 2025). "It should be a useful tool for investigating ciliopathy and the structure-function relationship of WDPCP and CPLANE." (PMID 41268724, 2025). "It contains several proteins, such as INTU, FUZ, WDPCP, JBTS17 and RSG1 (REM2- and RAB-like small GTPase 1), whose genes are mutated in ciliopathies." (PMID 31562761, 2020). "For instance, 3 of 11 ciliopathy-like patients carried heterozygous pathogenic variants in ciliopathy genes, such as ALSM1, USH2A, and WDPCP, thus it might support the initial clinical suspicion." (PMID 29588463, 2018). "Interestingly, mutations in the WDPCP transcript, which regulates planar cell polarity and ciliogenesis, have also been reported in a patient with Bardet–Biedl syndrome (BBS), one of the first ciliopathy characterized." (PMID 27141300, 2016).
Obesity (3 papers, 2023 to 2024). Accumulation of substantial excess body fat. "In humans, mutations in WDPCP gene cause Bardet-Biedl Syndrome39 presenting with a variety of symptoms in different organs including obesity, blindness, and polydactyly." (PMID 37996473, 2023). "In family C, a novel homozygous nonsense mutation was observed in the BBS15/WDPCP gene with clinical features that overlapped with previous studies such as obesity, mild learning disability, speech difficulties, mild hearing impairment, and rod–cone dystrophy, also reported earlier." (PMID 37239474, 2023). "Mutations in WDPCP have been associated with Bardet‐Biedl syndrome (BBS), characterised by retinitis pigmentosa, obesity, kidney dysfunction polydactyly and hypogonadism, most commonly caused by pituitary defects." (PMID 37794731, 2024).
hypogonadism (2 papers, 2014 to 2024). A disorder characterized by decreased function of the gonads. "OTX1 deletion could affect neighboring genes, in particular the gene WDPCP in which mutations were associated with hypogonadism, cryptorchidism, micropenis, and renal abnormalities." (PMID 25203062, 2014).
Tinnitus (2 papers, 2021 to 2025). Tinnitus is an auditory perception that can be described as the experience of sound, in the ear or in the head, in the absence of external acoustic stimulation. "Restructuring of synapses and neuronal circuitry is a common theme posited in each of these mechanisms; subsequently, WDPCP’s role in facilitating these structural changes could underscore tinnitus’s identity as a misdirected plasticity response within the DCN." (PMID 34518561, 2021).
liver cirrhosis (1 paper, 2023). "In our further MR analysis, we used publicly available databases derived from GWAS in human population and showed a link between the gene expression of WDPCP and liver fibrosis and liver cirrhosis." (PMID 37996473, 2023).
liver fibrosis (1 paper, 2023). "The gene expression of WDPCP in the human population supports a link to liver fibrosis." (PMID 37996473, 2023). "This evidence suggests that WDPCP might be an important gene involved in the pathway between alcohol consumption, accumulation of fat and liver fibrosis." (PMID 37996473, 2023).
nasal polyps (1 paper, 2020). "In this study, we sought to investigate the role of WDPCP and its underlying mechanism behind the dysfunction in the beating of cilia in nasal polyp tissue." (PMID 33598458, 2020). "In our previous study, we have previously discovered that the expression of WDPCP was reduced in the epithelial layer of nasal polyp tissues from patients with CRSwNP compared with control subjects, accompanied with cilia loss." (PMID 33598458, 2020). "According to immunohistochemical staining, we discovered that WDPCP was mainly expressed in the cytoplasm of nasal mucosa epithelium and the staining (brown color) was reduced in nasal polyp tissues." (PMID 33598458, 2020). "Our data showed that the low expression of WDPCP in nasal polyps was accompanied with a decreased frequency of cilia beating." (PMID 33598458, 2020). "Western blot also showed decreased protein expression of WDPCP in nasal polyp tissue compared with ethmoid sinus tissue from control subjects." (PMID 33598458, 2020). "Consistent with the protein levels, RT-PCR demonstrated a decrease of WDPCP mRNA levels in nasal polyps." (PMID 33598458, 2020). "With the dysfunction of cilia beating, we observed a low expression of WDPCP in the epithelium of nasal polyp tissues." (PMID 33598458, 2020). "We demonstrated WDPCP expression in the epithelium of nasal polyps." (PMID 33598458, 2020).
cancer (3 papers, 2021 to 2025). A tumor composed of atypical neoplastic, often pleomorphic cells that invade other tissues. "Further investigations to consider Fuz, Inturned and WDPCP as a functional group could unveil more pathogenic details of PCP effectors in cancer." (PMID 33658400, 2021). "Both short isoforms of WDPCP and RAB27B, which are induced by PRMT4, 5, and 7, promoted the proliferation of MCF7 cells, whereas the long isoform did so to a much lesser extent or even exhibited an opposite effect, thus linking aberrant splicing to cancer cell growth." (PMID 33782401, 2021).
neoplasms of the nervous system (1 paper, 2025). "First, BDNF, WDPCP, APC and SMO are associated with neoplasms of the nervous system, especially the pituitary gland (group BN)." (PMID 40831500, 2025).
tumor (1 paper, 2021). "Along with high levels of methylation of PRMT4, PRMT5, PRMT7, and hnRNPA1 in tumor samples, changes in gene alternative splicing were observed, such as those for PPARA, SREBF2, RAB27B, and WDPCP in BRCA, CRC, and PC samples." (PMID 33782401, 2021).
WDPCP also shares sentences with these, for which no sentence is quoted: Bardet-Biedl syndrome 15 (2 papers); cognitive deficits (2); acromelic frontonasal dysostosis (1); and retinal (1); autosomal recessive retinitis pigmentosa (1); bile duct cancer (1); Blindness (1); cancer of the liver (1); cataract (1); chronic rhinosinusitis (1); Cirrhosis (1); cryptorchidism (1); Doyne honeycomb retinal dystrophy (1); hepatocellular carcinoma (1); Joubert syndrome (1); Leber congenital amaurosis (1); liver cysts (1); Meckel Gruber syndrome (1); Micropenis (1); postaxial polydactyly (1); psychiatric disease (1); renal disease (1); retinitis pigmentosa (1); Rod-cone dystrophy (1); short rib-polydactyly syndrome (1); thoracic aortic aneurysm (1); Truncal obesity (1).